AFP (alpha fetoprotein)
Diseases named in the same sentence as AFP in open-access papers (continued):
Sharing a sentence is not in itself a finding about the gene and the disease.
liver disease (continued). "It was impossible to determine the PIVKA II and AFP performances, depending on the etiology of the liver diseases, with mixed etiology being taken into consideration." (PMID 36899960, 2023). "The median of the alpha-fetoprotein (AFP) level and model for end-stage liver disease score was 10.1 ng/mL and 11, respectively." (PMID 37909200, 2023). "The deep learning model trained with CEUS cines, AFP and liver disease showed the highest performance." (PMID 37958282, 2023). "Fourth, due to the small number of patients, we were unable to analyze more related factors and predicting biomarker in the survival analysis, such as tumor responses, PVTT, male, baseline AFP level and liver disease history." (PMID 37215117, 2023). "In conclusion, the current study improves our understanding of the role of IL-34 and AFP in HBV related liver disease." (PMID 35347503, 2023). "Many patients with HCC have no obvious specific symptoms at the early stage, and HCC is discovered incidentally during liver disease follow-up or physical examination in combination with liver ultrasound and alpha-fetoprotein (AFP) measurement." (PMID 36429000, 2022). "When pregnancy, active liver disease, and gastrointestinal tumors are excluded, AFP ≥ 400 μg/l is highly suggestive of HCC." (PMID 36203532, 2022). "Patients tested after the age of 3 months and after resolution of the active liver disease had consistently normal or marginally elevated AFP levels." (PMID 35455589, 2022). "Maternal serum AFP levels taken as part of the routine pregnancy screen were within normal limits in all examined cases, implying that the liver disease in NPC1 probably begins postnatally." (PMID 35455589, 2022). "Age, tumor size, NLR, PLR, and APRI were used to construct nomogram for OS, while gender, age, TNM stage, portal hypertension, AFP, APRI were for PFS." (PMID 33046985, 2020). "Biochemical indexes of hepatic function were consistent with a compensated liver disease, while the mean alpha-fetoprotein levels (24.8 μg/L) were above the reference value of 7 μg/L." (PMID 33585212, 2020). "The prognostic scoring systems currently available to predict survival in HCC patients before resection or transplantation involve variables such as the tumor size and number, serum alpha-fetoprotein (AFP), and underlying liver disease." (PMID 32631357, 2020). "Serum AFP level was observed to gradually increase with the progression of liver disease (one-way ANOVA, f-value = 2.906, p = 0.01)." (PMID 31968558, 2020). "The triplex miRNA panel demonstrated a higher diagnostic accuracy and reliability compared to the biomarker AFP alone in differentiating individuals with HCC from other groups of patients with HBV-related liver diseases." (PMID 29672637, 2018). "The strongest predictors among all liver disease etiologies were: older age, male sex, Hispanic ethnicity, high serum AFP level, alkaline phosphatase level and AST/√ALT ratio, and low platelet count and serum albumin level." (PMID 30260995, 2018). "In the present study, 156 (42.3%) HCC patients and 149 (85.1%) liver disease patients had an AFP level less than 20 ng/mL." (PMID 30545306, 2018). "Alpha‐fetoprotein (AFP), as the traditional marker of liver diseases, has been used for HCC diagnosis in the clinic." (PMID 29321958, 2018). "In univariable analyses, the most important predictors of HCC among all liver disease etiologies were older age, male sex, Hispanic ethnicity, high serum AFP level, alkaline phosphatase level and AST/√ALT ratio, and low platelet count and serum albumin level." (PMID 30260995, 2018). "The HCC group was significantly associated with HCV infection (OR 26.84; p<0.0001), higher levels of serum alpha-fetoprotein (OR 5.51; p=0.015), clinical portal hypertension (OR 0.25; p=0.032) and similar MELD score (p=0.693)." (PMID 29947694, 2018).
liver disease (continued). "In conclusion, the three miRNAs miR-21, miR-122 and miR-192 were differentially expressed in patients with different stages of HBV-related liver disease progression and correlated with AFP levels." (PMID 29672637, 2018). "The Mir@AFP panel was rather able to discriminate HCC from other HBV-related liver disease groups, especially from LC patients, compared to either the triplex miRNA panel or AFP alone." (PMID 29672637, 2018). "The basis of diagnosis of ICC was rarely done by histology (6.9%), and it is possible that other cases of fatal liver disease showing features of biliary obstruction, with a low serum alpha-fetoprotein, were possibly included in the case group." (PMID 30139338, 2018). "Increased alpha-fetoprotein (AFP) is usually resulting from liver disease and changes at its glycoform is a good indicator of disease progression." (PMID 29379771, 2017). "The present study aimed to develop a simple method to identify HCC in AFP-elevated liver diseases based on combining serum fluorescence and general clinical data." (PMID 29228649, 2017). "In the present study, we sought to develop a method to identify HCC in the liver diseases with elevated serum AFP levels." (PMID 29228649, 2017). "In the present study, we developed a method for identifying HCC in liver diseases with elevated AFP levels." (PMID 29228649, 2017). "At multivariate analysis using Cox's model alpha-fetoprotein, coarse large nodular pattern, portal hypertension, and age were independent predictors of HCC development." (PMID 28638828, 2017). "The initial model comprised the following covariates: HCC status (iHCC vs kHCC), length within waiting list, pre-LT alpha-fetoprotein, aetiology of liver disease (hepatitis C), Milan criteria fulfillment, microvascular invasion and tumor differentiation." (PMID 28403219, 2017). "In conclusion, we developed a simple but powerful method to identify HCC among liver diseases with serum AFP levels greater than 7 ng/ml." (PMID 29228649, 2017). "Although the method we developed in the present study is useful for identifying HCC in liver diseases with increases in serum AFP, it should be evaluated and confirmed by multicenter studies with a larger sample size." (PMID 29228649, 2017). "It takes into account the individual’s AFP history as well as his/her most recent six AFPs and other information: specifically, aetiology of liver disease." (PMID 27308823, 2016). "And this type HCC was distinctively associated with higher HBV infection rate, lower presence of background liver disease, younger age, higher serum AFP level, poorer differentiated histology, higher microvascular invasion rate, and poorer survival rate." (PMID 26266378, 2015). "Quantitative determination of serum AFP > 400 ng/ml lasting four weeks is valuable for the diagnosis of primary liver cancer, after excepting of active liver disease, embryonic gonad tumors and pregnancy cases." (PMID 25165471, 2014). "Some of the studies did not even report the follow-up time, Child-Pugh score, tumor size, background liver diseases and alpha-fetoprotein (AFP)." (PMID 22916174, 2012). "From the many possible biomarkers proposed for liver diseases, only a few are accepted for use and only one which is called fucosylated Alpha-fetoprotein (AFP) is a United States Food and Drug Administration approved biomarker." (PMID 22518319, 2012). "The rationale behind AFP treatment is either to overcome existing portal hypertension or to prevent its development." (PMID 23077458, 2012). "HCV was the underlying etiology of liver disease in 32 patients control and 30 HCC cases of which 12 were AFP-low HCC." (PMID 21092242, 2010). "Elevated AFP levels in some cases may be related to IMT stimulating hepatocyte proliferation or concurrent active liver disease." (PMID 40760522, 2025). "In the 2010 guidelines published by the American Association for the Study of Liver Diseases, AFP was not recommended for use in identifying HCC41." (PMID 39753619, 2025).
liver disease (continued). "Elevated AFP levels are often indicative of malignant liver disease." (PMID 40125297, 2025). "AI-enhanced liver stiffness measurement (LSM) trends may surpass alpha-fetoprotein (AFP) in predicting HCC risk, particularly in metabolic dysfunction-associated steatotic liver disease (MASLD), where AFP sensitivity is limited." (PMID 40361905, 2025). "Additionally, the American Association for the Study of Liver Diseases (AASLD) guidelines suggest the optional use of a combination of US and of alpha-fetoprotein (AFP)." (PMID 39857948, 2025). "Not all HCC tumors secrete AFP, and its levels can fluctuate depending on the tumor size, grade, and the presence of underlying liver disease." (PMID 39682122, 2024). "In our study 39 out of 90 HCC cases (43.3%) exhibited diagnostic AFP levels (above 400 ng/mL), 24 of viral, and 15 of nonviral etiology of liver disease." (PMID 38361401, 2024). "The blue line in the figure below represents the mean serum AFP (ng/mL) at various time ranges in full-term infants without factors known to be associated with elevated AFP values (premature birth, liver disease, hyperbilirubinemia)." (PMID 39224747, 2024). "However, the relative change in IgG (Δ-IgG) independently predicted OS in multivariable Cox regression analysis after adjusting for severity of liver disease, baseline AFP and CRP as well as for Δ-IgA and Δ-IgM." (PMID 37027398, 2023). "Current guidelines from the American Association for the Study of Liver Disease recommend biennial followups with abdominal ultrasonography, with or without alpha-fetoprotein (AFP)." (PMID 37628834, 2023). "In the multivariate analysis, larger tumor size, multinodularity, older age, male, higher alpha‐fetoprotein (AFP), higher albumin‐bilirubin (ALBI) grade, and the presence of portal hypertension were significantly associated with higher recurrence and decreased survival rates." (PMID 36016484, 2023). "The measurement of AFP is not recommended as a screening for liver tumours, because many other factors, including individual variation, age, pregnancy, inflammation and other liver diseases, may change AFP levels in horses." (PMID 36495211, 2023). "No significant change in AFP levels was observed over time (p = 0.199), despite the shift in etiology of the underlying liver disease." (PMID 37958389, 2023). "The American Association for the Study of Liver Diseases recommends biannual surveillance using US, with or without AFP." (PMID 36671786, 2023). "Importantly, there were significant differences (p < 0.0001) in the alanine transaminase enzyme (ALT) and α-fetoprotein (AFP) levels of patients with progressive chronic HCV liver disease." (PMID 37239415, 2023). "Our report suggests that biopsy should be considered for liver malignancies with abnormally elevated AFP levels and without underlying liver disease, particularly in young females." (PMID 38115376, 2023). "The study enrolled 292 patients with BCLC stage B or C disease that was refractory or not amenable to locoregional therapy, with Child–Pugh class A liver disease and serum AFP concentrations of 400 ng/mL or higher, and who had received previous treatment only with sorafenib." (PMID 36430594, 2022). "Although no patients with non-malignant liver diseases were detected with CTCs, the presence of CTCs was associated with AFP level and vascular invasion." (PMID 36091119, 2022). "Serum AFP, though widely used as a biomarker for the diagnosis of HCC, lacks specificity for patient surveillance particularly in cirrhotic patients with viral infection or underlying liver disease." (PMID 36358817, 2022). "Alpha-fetoprotein (AFP), a secreted glycoprotein, is abundantly expressed in the fetus and declines after birth; therefore, its elevation indicates an underlying pathology including hepatic disorders and malignancies, such as HCC." (PMID 36613878, 2022).
liver disease (continued). "The updated American Association for the Study of Liver Disease (AASLD) guidelines no longer recommended AFP testing as part of HCC diagnostic criteria." (PMID 36091119, 2022). "The covariates adjusted for PFS were maximal tumor size, tumor number, and bilirubin and albumin concentrations, whereas the covariates adjusted for OS were maximal tumor size; tumor number; sex; bilirubin, albumin, and AFP concentrations; and portal hypertension." (PMID 35626044, 2022). "Future studies may further explore combining other protein biomarkers and patient characteristics, such as age, gender, and liver disease etiology, with AFP and Deep MALDI mass spectral data using modern machine learning methods." (PMID 34206321, 2021). "To date, ALT and AFP have been widely used for the assessment of liver disorders." (PMID 33865328, 2021). "In addition to common risk factors associated with survival in patients with liver disease, such as TBil, INR, Cr, Na, and HE, the nomogram developed in this study included age, AST, AFP, PreLD, HBV DNA, WBC count, and Hb." (PMID 34222294, 2021). "The HBV-HCC and HCV-HCC patient median plasma levels of AFP, AFU, and HGF were found to be significantly higher than those of the CH and LC patients, indicating that a high expression of these biomarkers was associated with the progression of liver disease." (PMID 33628599, 2021). "The use of serum AFP levels for HCC surveillance is not recommended by the American Association for the Study of Liver Diseases due to the lack of specificity." (PMID 32071283, 2020). "Nonetheless, liver disease, other solid tumors with AFP production, or a genetic persistence of AFP may also lead to increased levels." (PMID 32235691, 2020). "In terms of our related results, the invaded area of the rRPS, maximum tumor size, AFP, portal hypertension, and presence of PV/HV branch invasion were significant as prognostic factors for OS in the univariate analysis, which is consistent with literature reports." (PMID 33072569, 2020). "Similarly, the present study confirmed that elevation of serum AFP is based on liver disease progression and was unable to differentiate early-stage HCC from CHB or LC." (PMID 31968558, 2020). "This AFP value has the potential advantage over the lower cut off value of < 20 ng/ml in being less likely to include those with an elevated level due to active liver disease such as such as with chronic viral hepatitis." (PMID 32471447, 2020). "The combination of PTX3 with AFP may allow further identification of HCC in the HBV-related liver disease population." (PMID 33219288, 2020). "The AFP levels continuously decreased with the interruption of chemotherapeutic agents, indicating a chemotherapy-induced liver toxicity on the basis of pre-existing liver disease." (PMID 31906360, 2020). "Surveillance primarily involves imaging, most commonly by ultrasound with or without alpha-fetoprotein (AFP) every 6 months, as recommended by the recent guidelines from the American Association for the Study of Liver Diseases (AASLD)." (PMID 30675135, 2019). "Guidelines from the American Association for the Study of Liver Disease (AASLD) recommend HCC surveillance with abdominal ultrasound every 6 months with or without alpha fetoprotein (AFP) in patients with cirrhosis." (PMID 31399619, 2019). "In addition, we also analyzed the diagnostic performance of the Mir@AFP panel in discriminating HCC from other HBV-related liver diseases in patients with normal AFP levels." (PMID 29672637, 2018). "At present, the updated American Association for the Study of Liver Disease (AASLD) guidelines no longer recommend alpha-fetoprotein (AFP) testing as a part of diagnostic evaluation." (PMID 30176913, 2018). "The American Association for the Study of Liver Diseases guidelines (AASLD) no longer recommends AFP to be used for diagnosis." (PMID 29632649, 2018).
liver disease (continued). "The associations of serial measurements with serum levels of WFA+-M2BP, ALT, AST and AFP may facilitate clarifying the role of WFA+-M2BP during liver disease progression." (PMID 30237482, 2018). "Our data indicate that the combination of AFP and NLR offers better diagnostic performance than either marker alone for differentiating HCC from liver disease, which may benefit clinical screening." (PMID 30545306, 2018). "The American Association for the Study of Liver Diseases (AASLD) Practice Guidelines Committee recommended that ultrasound (US) exam alone be used for HCC surveillance due to the poor sensitivity and specificity of AFP in detecting early-stage HCC." (PMID 27070780, 2016). "AFP and platelet count are established measures of liver disease and HCC." (PMID 27688741, 2016). "However, these screening methodologies are unable to identify the molecular typing of HCC and preoperative tumor grade; AFP’s sensitivity in screening of HCC is very limited as increased level of AFP has been reported in many other liver diseases as well." (PMID 26658912, 2015). "Many studies have found that the level of serum DCP in patients with benign and malignant liver diseases is significantly different, and its diagnostic sensitivity may be higher than commonly used HCC markers such as AFP; however, this remains controversial." (PMID 25165471, 2014). "AFP levels above 20 ng/mL are considered indicative of possible liver disease." (PMID 24059753, 2013). "Some reports indicate that healthy individuals may have AFP levels of up to 20 ng/mL, and levels above this are considered to indicate the possibility of liver disease." (PMID 22559879, 2012). "In 1972, AFP (alpha-fetoprotein) testing continued, and in May and October, surveys were conducted on the population aged 16 and above and liver disease patients in the Huilong, Xiangyang, and Xining communes (townships), with a total of 71,585 people examined." (PMID 39998096, 2025). "Current surveillance strategies recommended by the European Association for the Study of the Liver (EASL) and the American Association for the Study of Liver Diseases (AASLD) primarily include ultrasound with or without alpha-fetoprotein (AFP) testing for high-risk populations." (PMID 40055844, 2025). "Guidelines from the American Association for the Study of Liver Disease (AASLD) recommend regular monitoring of individuals living with HBV at six-month intervals, with an assessment of liver function, HBV viral load, ultrasound, and alpha-fetoprotein (AFP) levels." (PMID 35457509, 2022). "Moreover, the presence of comorbidities (especially DM), portal hypertension, multinodular disease (with more than three tumoral masses), AFP levels higher than 300 ng/mL, high TBS, and nodule diameter larger than 6 cm indicate poor overall survival (p = 0.001)." (PMID 35800821, 2022). "The current guidelines from the American Association for the Study of Liver Diseases (AASLD) recommend that individuals with CHB receive regular monitoring every six months with abdominal ultrasound and blood tests for liver function, HBV load, and alpha-fetoprotein (AFP) levels." (PMID 36292391, 2022). "In addition, our previous work revealed that antiviral treatment could lower serum AFP levels in patients with HBV-related liver disease and improve the surveillance performance of serum AFP for early-stage HCC." (PMID 36016291, 2022). "Therefore, the Practice Guideline Committee of the American Association for the Study of Liver Disease (AASLD) does not recommend using AFP in the early detection of HCC." (PMID 35804809, 2022). "However, the fact that AFP could also be elevated in other benign liver diseases sparked controversy about the use of AFP for HCC surveillance." (PMID 35002508, 2022). "Therefore, the American Association for the Study of Liver Diseases (AASLD) Practice Guidelines Committee does not recommend AFP as the only means of early detection of HCC." (PMID 36341438, 2022).